AKT2 (AKT serine/threonine kinase 2)
Diseases named in the same sentence as AKT2 in open-access papers (continued):
Sharing a sentence is not in itself a finding about the gene and the disease.
tumor (continued). "In this present study, we found that depletion of Akt2 or Akt3 did not alter the tumor development or local invasion while we confirmed our prior data with the Akt1 knock out model." (PMID 33110146, 2020). "In addition, AKT2 (p = 0.002) and KAT6A (p = 0.015) amplifications were more frequent in tumor samples from younger patients (<60), and CEBPA (p = 0.028) and MYC (p = 0.023) amplifications were more common with advanced (stage III and IV) disease stage." (PMID 32877461, 2020). "Co-treatment with cisplatin in mice carrying xenografts formed from knockdown of AKT2 (4T1 shAKT2) and AKT3 (4T1 shAKT3) in 4T1 cells dramatically attenuated tumor formation in mice after two weeks as compared with that of mice with knockdown of AKT1 (4T1 shAKT1) treated with cisplatin." (PMID 33227065, 2020). "Both the British and Indian tumor histology patterns revealed higher expression of AKT2 while expressions of AKT1 and AKT3 were not significant when observed in both liver and lung metastasized FPPE samples." (PMID 33227065, 2020). "Some researchers have proposed that 8-Cl-cAMP may also exert PKA-independent anti-tumor effects through its metabolite 8-Cl-adenosine and AKT2–PKBβ pathway." (PMID 33292604, 2020). "AKT2 regulates the signal transduction initiated by PI3K, which is involved in many cellular processes including cell cycle regulation, apoptosis initiation, tumor angiogenesis, lymphangiogenesis, and cell invasion." (PMID 32211805, 2020). "Additional work is necessary to determine whether AKT2 and/or SGK3 are needed for tumor progression (that is, maintaining cancer growth once tumors are fully formed)." (PMID 30975125, 2019). "In addition to genes that were also modulated in lSSc samples (i.e., MYC, AKT2, and PIM1), other genes involved in cell proliferation and also in tumor development were overexpressed." (PMID 29559981, 2018). "Thus, while overexpression of AKT1 promoted local tumor growth, downregulation of AKT1 or overexpression of AKT2 promoted peritumoral invasion and lung metastasis." (PMID 28287129, 2017). "AKT2 represses GSK3β activity by increasing the phosphorylation level of GSK3β protein at Ser9 residues, and has been reported to be upregulated in CRC tissues compared to normal colon mucosa and promote tumor progression." (PMID 29258530, 2017). "However, when Akt2 KD cells were injected into WT C57BL/6 mice, there was a similar increase in tumor growth rate, suggesting that influences other than metabolism are responsible." (PMID 27533079, 2016). "Moreover, cotransfection with EGFR, AKT2, or CCND1 not only counterbalanced the tumor suppressor effects of miR-2861, but also promoted cancer cell growth and enhanced cell invasion ability." (PMID 27364926, 2016). "Unlike with the transient silencing, stable silencing of Akt2 strongly inhibited LNM35 tumor growth (532 mm3 +/−188, **P < 0.01) in comparison with control-shRNA (3431 mm3 +/−725)." (PMID 26234648, 2015). "We observed an increase in FoxO3a phosphorylation in WT and Akt1−/− mice concomitant with tumor burden, but FoxO3a phosphorylation remained constant in Akt2 and Akt3 mice irrespective of tumor burden." (PMID 24722238, 2014). "Together, our findings suggest that adding chloroquine to EGFR and AKT inhibition has the potential to improve tumor responses in EGFR M+ NSCLC, and that selective targeting of AKT2 may provide a new treatment option in NSCLC." (PMID 24946858, 2014). "Ablation of Akt1 or Akt2 significantly delayed tumor onset and tumor growth rate but did not significantly alter lung metastasis." (PMID 23919516, 2013). "Since the total level of Akt phosphorylation did not diminish despite the absence of Akt1 or Akt2, it appears that the tumor cells compensated by increasing the phosphorylation of the remaining Akt isoforms." (PMID 23919516, 2013).
tumor (continued). "We observed an unexpected trend towards improved TTP in patients with tumours with strong Akt2 expression (13.1 vs. 7.2 months) but the difference was not statistically significant (P=0.133; HR 0.682; 95% CI 0.42–1.12)." (PMID 22842582, 2012). "There were no Akt2-negative tumours, 45 (60.8%) samples were weak positive and 26 (35.1%) were strong positive on Akt2 staining, results for three tumours were not interpretable." (PMID 22842582, 2012). "Interestingly, tumours responded to trastuzumab by a sharp fivefold increase in phosphorylated AKT/PKB as well as a 3.5- and 5.3-fold increase in AKT1 and AKT2 mRNA levels, respectively." (PMID 18454161, 2008). "AKT2, a key player in the PI3K/AKT/mTOR signaling pathway, is frequently dysregulated in cancers, promoting tumor growth and therapeutic resistance The strong binding of complex 9 to AKT2 suggests its potential to disrupt this pathway, thereby inhibiting tumor proliferation." (PMID 40575462, 2025). "However, only Akt2-OE CTLs, not Akt1-OE CTLs, effectively eliminate tumor cells in vivo, accompanied by distinct exhaustion-related gene expression." (PMID 40139836, 2025). "However, in the HCC mouse model, Akt1-OE CTLs exhibited delayed effector function compared with Akt2-OE CTLs and failed to eliminate tumor cells initially." (PMID 40139836, 2025). "The upregulated usage of AKT2 isoform in the high‐risk OLGIM group lacked the kinase domain present in the canonical AKT2 isoform, which could indicate that increased levels of the isoform dysregulated signaling pathways, facilitating tumor progression." (PMID 39171503, 2024). "Notably, AKT2 did not display a significant difference in mRNA levels between tumour and normal groups (p = 0.0686)." (PMID 39063239, 2024). "On the other hand, for phagocytosis experiment, both silencing AKT1 and AKT2 reduced phagocytosis of dying cells, and silencing of both AKT1 and AKT2 reduced the expression of LC3‐II, which indicated that both AKT1 and AKT2 played roles in engulfment of dying tumor cells by macrophages." (PMID 35037422, 2022). "It is plausible that AKT2 rather than CCNE1 or CEBPA in this dataset is the driver of the tumor." (PMID 32877461, 2020). "AKT2 mRNA expression was not correlated with the tumor stages of patients with ccRCC (P > 0.05)." (PMID 32547875, 2020). "Furthermore, RAC-beta serine/threonine-protein kinase (AKT2) is frequently overexpressed, and the activity of its upstream regulator phosphoinositide 3-kinase (PI3K) is often elevated in PDAC leading to increased tumor cell survival." (PMID 31395068, 2019). "From these initial data, we cannot rule out the possibility that Akt2 or Akt3 may be more relevant in controlling the CSC phenotype in models from different tumour lineages." (PMID 29518912, 2018). "Furthermore, the three AGC kinases AKT-1, AKT-2, and SGK-1 that in most previous studies have displayed redundant activities as negative regulators of DAF-16, have antagonistic roles in DAF-16 mediated tumor formation." (PMID 28549065, 2017). "Previous reports suggested that AKT2 affected the development of tumors through relative signal pathways such as PI3K/AKT/c-myc pathway, which affected cell proliferation, migration and invasion of tumors, and induces cell apoptosis, and inhibited tumor growth in animal models in variety tumors." (PMID 29050238, 2017). "Similarly, knockdown of Akt1 and Akt3 significantly hampered cell proliferation in vitro and tumor growth in vivo, but Akt2 knockdown did not." (PMID 29090098, 2017). "Similarly, in T47D xenografts AKT1 silencing reduced tumor growth, whereas AKT2 silencing did not change the growth rate compared to control tumors." (PMID 28287129, 2017). "Similarly in a PDGFB-driven mouse model of low-grade glioma, transgenic expression of AKT2 or AKT3 but not AKT1 greatly accelerated tumour formation." (PMID 28082369, 2017).
tumor (continued). "Overall, our results suggest that targeting at the PI3K or AKT1/2 level would not be effective in preventing tumor progression, although specifically targeting AKT2-driven signals could be more effective at preventing cancer aggressiveness." (PMID 28287129, 2017). "No tumor developed in one mouse of the group xenografted with Akt2 silenced cells." (PMID 26234648, 2015). "Lastly, ablation of Akt2 does not increase mTOR activation as tumor burden increases." (PMID 24722238, 2014). "Erk1/2 signaling promotes survival and may have contributed to tumor cell survival in the absence of Akt2." (PMID 23919516, 2013). "We hypothesize that potential compensation by AKT1 might explain why the CRIPSR KO AKT2 cells did not recapitulate the decreased subcutaneous tumor growth or the full prophylactic protection observed for the shRNA AKT2 KD cells, although we have not explicitly tested this hypothesis." (PMID 37894325, 2023). "Although AKT2 (v-akt murine thymoma viral oncogene homolog 2) was down-regulated in all three cancer nodules (x = −1.65 in “A”, −1.61 in “B” and −1.94 in “C”), AR (androgen receptor) was not affected and therefore the tumor did not regress as expected in the androgen-deprivation therapy." (PMID 34209090, 2021). "However, we did not observe any effect on the apoptosis of tumor cells after inhibiting the expression of AKT2, indicating that AKT2 may control cell proliferation via cell cycle regulation." (PMID 32873299, 2020). "Specifically, MYC showed positive correlations with oncogenic factors HDAC2, HDAC3, AKT2, and AKT3, while demonstrating negative correlations with tumor suppressors PTEN and FOXO1." (PMID 40229260, 2025). "We observed a decrease in calcified bone volume after inoculation of 231-BO cells with AKT2 knockdown, AKT3 knockdown, and SCR control vector compared to NSG mice without tumor cell inoculation." (PMID 33670586, 2021). "Interestingly, in the comparison of CSP/CNSP groups, the genes AKT2, AKT3, and PTEN also exhibit a significant increase in expression in normal tissue but not in tumor tissue." (PMID 38505269, 2024). "Interestingly, this connects to a recently published work on Akt inhibitor resistance in castration-resistant prostate cancer (CRPC), where the authors also observed specific upregulation of Akt3, but not Akt1 or Akt2, in MK2206-resistance tumor cells." (PMID 36291790, 2022). "The tumor suppresser, 12-O-Tetradecanoyl phorbol-13-acetate (TPA)-inducible sequences 21 (TIS21), an ortholog of B-cell translocation gene 2 (BTG2), inhibited TNBC cell growth and invasion via activation of Akt1 and not Akt2." (PMID 34298660, 2021). "Furthermore, knockdown of AKT2 in the mice results in enhanced proliferative capacity and tumor growth, whereas ablation of AKT3 has a slight non-significant effect by attenuating tumor growth and induction." (PMID 31752925, 2019). "In BCPAP cells treated for 72 h, genes from the canonical Wnt pathway (FZD1, DVL1, AKT2, CTNNB1, LEF1, MYC) and the non-canonical Wnt pathway (RHOA, related to cytoskeletal dynamics and increased migration and invasion) were upregulated, suggesting pro-tumor behavior." (PMID 39125748, 2024).
cancer (256 papers, 2008 to 2026). A tumor composed of atypical neoplastic, often pleomorphic cells that invade other tissues. "This study underscores the importance of genetic screening in optimizing cancer treatment and highlights the need for mutation-specific therapeutic strategies targeting AKT2." (PMID 41144441, 2025). "The BCAM–AKT2 fusion gene generates a membrane-associated, constitutively activated AKT2 protein kinase, likely contributing significantly to cancer progression via the PI3K/AKT signaling pathway." (PMID 39000374, 2024). "Akt2 is highly expressed in many human cancers and is closely associated with cancer cell metabolism, proliferation, cell survival, metastasis, angiogenesis and drug resistance." (PMID 39334719, 2024). "β-Catenin, AKT2, and pyrimidine synthesis inhibitors are promising therapeutics for the treatment of oncogenic β-catenin–associated cancer." (PMID 36122209, 2022). "The causality of the CTNNB1 mutation and hepatocarcinogenesis thus confers AKT2/CAD signaling cascade-mediated pyrimidine synthesis a druggable vulnerability for CTNNB1 mutant cancer." (PMID 36122209, 2022). "Accumulating evidence showed that miRNAs play a crucial role in the pathogenesis of tumors, and numerous miRNAs responsible for modulation of Akt2 resulted in important diagnostic, prognostic, and therapeutic markers in various cancers." (PMID 35743776, 2022). "Hypoxia-induced AKT2 can induce cancer proliferation, while downregulated AKT2 is linked with cell cycle arrest and reduced proliferation." (PMID 33808426, 2021). "Among these three, AKT2 is much more closely associated with cancer cell metabolism, proliferation, cell survival, metastasis, angiogenesis and drug resistance." (PMID 32873299, 2020). "While attempting to clone AKT2 by PCR from a cDNA library from cancer-tissue, we unexpectedly identified a splice variant of AKT2 that lacked the HM regulatory site." (PMID 33253205, 2020). "Our survey of published cancer sequencing data identified five AKT2 kinase domain mutations that occurred in at least two independent samples (G161V/E, R170W, I289M, H355Y, R368C/H)." (PMID 25551293, 2014). "AKT is infrequently mutated in human cancer but AKT2 gene can undergo amplification in certain cancers." (PMID 21422497, 2011). "It was previously shown that Akt2 was physically associated with the mitochondria in a variety of cancer cell lines including MDA-MB231." (PMID 21297943, 2011). "However, somatic mutations in the AKT2 gene, particularly within its kinase domain, have been implicated in cancer development." (PMID 41144441, 2025). "Also, transcript pairs from AKT2, involved in all cancer hallmark processes except genome instability were phase-shifted in HCT116_WT." (PMID 35552415, 2022). "These included many cancer-associated genes such as AKT2, HRAS, TGFBI and UBE2C." (PMID 32437477, 2020). "With this in mind, the H1047R mutation might prove to be a useful biomarker for AKT2 isoform activation in cancer patients with metastasis." (PMID 30012111, 2018). "Moreover, both AKT1 rs2294750 and AKT2 rs7254617 polymorphisms have been investigated in cancers among Chinese populations 9, 19, but results are conflicting." (PMID 26828791, 2016). "Of the three AKT isoforms, AKT2 has been implicated more frequently in cancers." (PMID 23468863, 2013). "In addition to somatic mutation, overexpression of AKT isoforms, particularly AKT2, has been reported in multiple human cancers." (PMID 22666248, 2012). "Among the members of Akt family, Akt2 is associated with the development of human cancers." (PMID 21686164, 2011). "This study highlights the critical role of nsSNPs in influencing the efficacy of AKT2 inhibitors, with significant implications for targeted cancer therapy." (PMID 41144441, 2025). "Overall, the varying effects of these mutations on inhibitor activity have significant implications for AKT2 targeted cancer therapy." (PMID 41144441, 2025).
cancer (continued). "Collectively, these findings emphasize the critical need to consider deleterious mutations into future drug development and clinical strategies to overcome resistance and improve therapeutic outcomes in AKT2-driven cancers." (PMID 41144441, 2025). "Our results indicated a significant upregulation of AKT2 mRNA levels in blood cancer patients compared to healthy controls." (PMID 38577021, 2024). "RT-qPCR was used to analyze AKT2 gene mRNA and miRNA-4716–3p expression in 200 blood cancer samples and 200 healthy controls." (PMID 38577021, 2024). "The uncharacterized isoform switch in AKT2 merits attention, as it has been shown that the AKT2 isoforms have been suggested to play a specific role in cancer progression." (PMID 39171503, 2024). "In this study, we specifically investigated the microRNA-4716–3p, its target AKT2 gene, and rs2304186 variations of blood cancer patients alongside healthy individuals to discern potential biomarkers for non-invasive prognostic and diagnostic purposes." (PMID 38577021, 2024). "This makes MUL1 an interesting target for a therapeutic strategy aimed at reducing the levels of Akt (and especially Akt2) in cancers that overexpress it such as breast, lung and colon cancer." (PMID 38139010, 2023). "Each Akt isoform has been demonstrated to play different and specific roles in cancer cells signaling; indeed, Akt1 and Akt2 displayed opposite roles in cell cycle progression, migration and invasion among different types of human cancers." (PMID 36769122, 2023). "As an example, AKT1 has been shown to suppress breast cancer cell migration and invasion in in vitro studies, while AKT2 promotes these processes, potentially facilitating cancer metastasis." (PMID 37513905, 2023). "We corroborated, using novel ways of correlating absolute SCNA with transcriptomics, that in our organoid models, the correlation was highest for MYC, PIK3CA, and AKT2 reinforcing their putative role as potential targetable cancer drivers." (PMID 37166279, 2023). "In fact, its absence leads to the accumulation of targets like Akt2, a well-known mediator of cancer cell survival, and to an overall higher activation of Akt." (PMID 38139010, 2023). "TAS-117 inhibits the proliferation of various human cancer cell lines in vitro, including breast, endometrial, lung and ovarian cancer cells with Akt2 or human epidermal growth factor type 2 (HER2) gene amplification, PIK3C mutations or PTEN loss." (PMID 36180910, 2022). "Accordingly, we searched the literature via Google Scholar and PubMed and found novel information for networking the AKT1-, AKT2-, and AKT3-associated circRNAs and cell functions, especially for cancer cells." (PMID 36230902, 2022). "AKT2 phosphorylates WASP-interacting protein by AKT2 thereby stabilizing YAP/TAZ transcriptional factors to support cancer stem cell survival and phenotype." (PMID 36567312, 2022). "Fifteen (11.9%) cancers harbored 16 PI3K pathway mutations: PIK3CA (n = 7), AKT2 and RICTOR (n = 3 each), PTEN, PIK3C2B, and PIK3R1 (n = 1 each)." (PMID 36124727, 2022). "Protein kinase B and its three paralogs, akt1, akt2, and akt3, exhibit intensively deliberated cancer and metabolism, and also regulate the plasma membrane and cell size mutations in Drosophila." (PMID 36362447, 2022). "JIB-04 interfered with the cell cycle progression of HCC cells and cancer stem-like cell properties via the AKT2-FOXO3a-RB axis by inhibiting the histone demethylase activity of KDM6B on the AKT2 promoter." (PMID 35887001, 2022). "The oncogene AKT2 is triggered by amplification or overexpression in a variety of malignant tumors, thus facilitating tumor invasion and metastasis." (PMID 35402264, 2022). "We focused our studies on Akt2 and HIF-1α coregulation by MUL1 since activation of these proteins is involved in metabolic phenotypes that favors glycolysis, a hallmark of cancer cells referred to as the Warburg effect." (PMID 35846359, 2022).